BRCA1 (BRCA1 DNA repair associated)
Diseases named in the same sentence as BRCA1 in open-access papers (continued):
Sharing a sentence is not in itself a finding about the gene and the disease.
breast cancer (continued). "Only 5–10% of breast cancer cases are caused by genetic inheritance of the breast cancer 1/2 (BRCA1/2) gene mutations." (PMID 33925065, 2021). "A homozygous frameshift mutation in BRCA1 called BRCA1-AA2800 that creates a truncated protein of 900 amino acids was reported in a patient with breast cancer." (PMID 33923105, 2021). "Another patient diagnosed with early onset bilateral breast cancer had an in-frame variant with conflicting interpretations of pathogenicity rs80358343 (c.5017_5019delCAC) in the BRCA1 gene." (PMID 34490083, 2021). "Hereditary breast cancer accounts for up to 5–10% of all breast cancers with two high-penetrance genes (BRCA1 and BRCA2) responsible for about 16% of the familial risk of breast cancers, associated with a 60–80% lifetime risk of developing breast cancer." (PMID 32725533, 2021). "To address this, we resorted to the Fluidigm C1 platform based scRNA-seq to decipher the composition of BRCA1-deficient mammary tumor cells, as well as the mammary luminal cells, in which loss of BRCA1 initiates the tumorigenesis." (PMID 34815798, 2021). "It has been estimated that the average man has less than 1% lifetime risk of developing breast cancer (BC), but for men who harbor a BRCA1- or BRCA2- mutation, this risk amplifies significantly." (PMID 34575694, 2021). "Upon identification of the model with the best predictive performance, i.e., the optimized random forest, it has been applied to predict the BRCA1 VUS pathogenic risks for ovarian/breast cancer." (PMID 33937409, 2021). "For a long time, breast cancer was considered a disease with genetic origins, predominantly resulting from mutations in key genes such as BRCA1 and BRCA2." (PMID 34884658, 2021). "Approximately 50% of all hereditary breast cancer cases are due to BRCA1/2 CPG mutations and are associated with early-onset breast cancer." (PMID 34070674, 2021). "Overall, germline BRCA1 mutated cancers had significantly higher cyclin E1 protein than the BRCA1 wildtype cases, and tumors with other breast cancer associated germline mutations (BRCA2, PALB2, or CHEK2)." (PMID 34465787, 2021). "Female breast cancer patients with a BRCA1 or BRCA2 pathogenic variant have an increased risk of a second primary breast cancer and/or ovarian cancer." (PMID 33319336, 2021). "These patients also have an elevated risk of developing contralateral breast cancer, with a cumulative incidence up to 83% for BRCA1 and 62% for BRCA2 carriers." (PMID 34285295, 2021). "The Breast Cancer Susceptibility Gene 1 (BRCA1) and the Breast Cancer Susceptibility Gene 2 (BRCA 2) are tumor suppressor genes that encode proteins involved in the repair of DNA double-strand breaks by way of the homologous recombination repair pathway." (PMID 33504079, 2021). "In an individual with a pathogenic variant of BRCA1, the cumulative risk for breast cancer and ovarian cancer at 80 years of age is 72% and 44%, respectively." (PMID 32948841, 2021). "The 5-, 10-, and 15-year cumulative CBC risk of 810 female BRCA1/2 breast cancer patients is 13.7%, 23.8%, and 36.1% for BRCA1 and 12.0%, 18.7%, and 28.5% for BRCA2, respectively." (PMID 32862296, 2021). "BRCA1-related breast cancer is often associated with triple negative breast cancer (TNBC) subtype, whereas BRCA2-associated tumors tend to be luminal-like breast cancer." (PMID 34202525, 2021). "A previous case–control study conducted in our center has shown 4.0% of metachronous contralateral breast cancer recurrence in BRCA1/2-negative patients with risk factors for hereditary breast and/or ovarian cancer." (PMID 34285295, 2021). "Genetic and metabolic alterations in basal-like and BRCA1-associated breast cancer can lead to chronic high levels of ROS, increasing the level of AhR protein and its transcriptional activity." (PMID 33451095, 2021).
breast cancer (continued). "Any loss of detection sensitivity for BRCA1/2 actionable variants in breast cancer panels should lead to bespoke BRCA1/2 testing being conducted first." (PMID 34439310, 2021). "In Caribbean-born women and men with breast cancer, having a first- or second-degree family member with breast cancer was associated with having any BRCA1 or BRCA2 germline variant (odds ratio, 1.58; 95% CI, 1.24-2.01; P < .001)." (PMID 33646313, 2021). "Basal-like breast cancers commonly arise in high-risk women carrying BRCA1 mutations, and are known for their aggressiveness and resistance to chemotherapy." (PMID 35187501, 2021). "Initial studies using the three FDA-approved drugs showed selective killing of BRCA1-mutated breast cancer cells, BRCA2-mutated ovarian cancer cells (PE01), and BRCA1-mutated ovarian cancer cells (UWB1.289)." (PMID 33784323, 2021). "For a few years, PARPi has shown promising activity as a chemotherapeutic agent in BRCA1- or BRCA2-associated breast cancers, and in combination with chemotherapy in triple-negative breast cancer." (PMID 34829741, 2021). "We show that reducing Sox11 levels in the Brca1-deficient mammary tumour (Brca1.3) has similar effects on proliferation, stem cell activity and expression of lineage markers to those observed in studies using embryonic mammary progenitor cells (eG2M5)." (PMID 33969421, 2021). "Analysis of the serum zinc levels has revealed a tendency toward an increased risk of breast cancer for unselected breast cancers and among BRCA1 carriers with low zinc levels." (PMID 34200699, 2021). "In a seminal study published by King and colleagues, two modifiable risk factors were associated with breast cancer penetrance in BRCA1/2 mutation carriers—obesity and physical activity." (PMID 33649363, 2021). "The cumulative breast cancer risk to age 80 years is 72% (95% CI, 65%–79%) for female with BRCA1 mutation and 69% (95% CI, 61%–77%) for female with BRCA2 mutation." (PMID 33996049, 2021). "Women were defined as high risk if they had a germline mutation that greatly increases lifetime risk of a breast cancer diagnosis including BRCA1, BRCA2 and PALB2 (refs.2,18)." (PMID 35187501, 2021). "EZH2 has been shown to be overexpressed in a number of tumours including BRCA1-deficient breast cancers." (PMID 34287743, 2021). "After 10 years of follow-up, the cumulative incidence of breast cancer was significantly lower for BRCA1/2 mutation carriers who used ET (12%) compared to those who used EPT (22%; P = 0.04)." (PMID 33885953, 2021). "Increasing numbers of first-degree and second-degree family members with breast cancer were associated with higher odds of having a BRCA1 (OR, 1.93; 95% CI, 1.68-2.21; P < .001) and a BRCA2 variant (OR, 1.52; 95% CI, 1.26-1.85; P < .001)." (PMID 33646313, 2021). "One in eight women will be diagnosed with breast cancer in their lifetime, but only 5–10% of these women have a BRCA1 and/or BRCA2 (BReast CAncer) genetic mutation." (PMID 34969949, 2021). "It has been shown that breast cancer with a BRCA1 mutation is more often associated with medullary-like histopathology, TNBC and basal phenotype." (PMID 33918338, 2021). "Recent reports have identified as high as 11.1% germline BRCA1 mutation in a risk-enriched cohort of Taiwanese breast cancer patients." (PMID 34574977, 2021). "Very important discoveries regarding the etiology of breast cancer concern the mutations in the BRCA1/2 genes." (PMID 33925599, 2021).
breast cancer (continued). "In the present study, concomitant contralateral RRM was significantly more prevalent in breast cancer patients whose BRCA1/2 mutations were identified prior to surgery." (PMID 34285295, 2021). "In this cohort of postmenopausal breast cancer patients, 10.2% harbored pathogenic germline BRCA1/BRCA2 variants; 11.7% of these patients had at least one family member who was affected with breast, ovarian, prostate, or pancreatic cancer." (PMID 34287479, 2021). "Our work offers the first genetic and biochemical evidence that PDGFRβ-PKCα signaling is repressed by BRCA1, which establishes PDGFRβ-PKCα signaling as a therapeutic target for BRCA1-deficient breast cancers." (PMID 33478572, 2021). "Next, we examined the association between cyclin E1 expression and overall survival in germline BRCA1 mutated breast cancers in our cohort." (PMID 34465787, 2021). "PR status was significantly different between BRCA1 and BRCA2 mutation carriers; BRCA2 carriers are more likely to develop progesterone receptor (PR) positive tumors and PR-negative breast cancer are associated with BRCA1 mutation carriers (p=0.000084)." (PMID 34490083, 2021). "Along with activation of the Akt pathway, estrogen promoted EMT and proliferation in BRCA1-deficient mammary tumor cells." (PMID 33540843, 2021). "ATM and CHEK2 are recognized as the most common breast cancer susceptibility genes, and their attenuation is associated with BRCAness, namely phenocopies of BRCA1/2 defects." (PMID 35008774, 2021). "Though PARP inhibition has led to significant success in the treatment of BCRA1/2 breast cancer, more than 40% of BRCA1/2-deficient breast cancer patients are unresponsive to PARPi therapy." (PMID 34070674, 2021). "A small fraction of breast cancers (~1–5%) can be attributed to familial mutations in the BRCA1 and 2 cancer susceptibility genes; such mutations confer an elevated lifetime risk of breast, ovarian, and other cancers." (PMID 33513753, 2021). "Patients harboring BRCA1/2-mutated breast cancer tend to have an earlier age at onset—usually before 50 years of age, particularly for BRCA1 cancers, and a higher risk for contralateral breast cancer." (PMID 34070748, 2021). "Upregulated expression of HIF1α and VEGF have been observed in BRCA1/2-mutated hereditary breast cancer when compared to sporadic breast cancer." (PMID 35008272, 2021). "A retrospective cohort study, GENE-RAD-RISK, reported a relationship between medical radiation exposure, including mammography and breast cancer in 1,993 women with unaffected BRCA1/2 mutations." (PMID 32862296, 2021). "Considering hereditary BC tumors, most cases are due to germline mutations in the breast cancer genes BRCA1/2." (PMID 33803776, 2021). "Whereas, the Filamin A isoform has been shown to inhibit tumor progression by regulating breast cancer type 1 susceptibility protein (BRCA1) expression in human breast cancer." (PMID 33672325, 2021). "Generally, women who harbor BRCA1/BRCA2 mutations are more frequently diagnosed with breast cancer at an early age (≤40 years) or with ovarian cancer at any age." (PMID 34287479, 2021). "Among 73 breast cancer patients with detectable P/LP variants, BRCA1 and BRCA2 accounted for 58 patients (79.5%)." (PMID 33649982, 2021). "In BRCA1-associated breast cancer, irradiation-induced DNA breakage increases the lethality against BRCA1-mutant tumor cells, while allowing surrounding normal tissue to survive by virtue of continued appropriate DNA repair activity." (PMID 33767581, 2021). "Remarkably, in breast cancer with mutated BRCA1, β-hCG can signal through transforming growth factor beta receptor II (TGFβRII) regardless of the hCG/LH-R status, resulting in increased cell proliferation." (PMID 34359928, 2021). "As part of a larger prospective study on heavy metals, our aim was to investigate if blood arsenic levels are associated with breast cancer risk among women with inherited BRCA1 mutations." (PMID 34283078, 2021).
breast cancer (continued). "The phase II TBCRC 048 trial (NCT03344965) assessed olaparib response in metastatic breast cancer patients with germline mutations of non-BRCA1/2 HR-related genes (cohort 1) and somatic mutations of BRCA1/2 or other HR-related genes (cohort 2)." (PMID 34778045, 2021). "In women with a BRCA1 mutation, the probability of developing breast cancer over her lifetime is 57–65%." (PMID 34711195, 2021). "The BRCA gene plays an important role in the homologous recombination mechanism of DNA repairing, and the germline BRCA1/2 mutations will significantly increase the risk of breast cancer in females." (PMID 33407485, 2021). "Several retrospective studies suggested that risk-reducing bilateral salpingo-oophorectomy (RRBSO) is associated with reduction in risk not only for ovarian and fallopian tube cancer, but also for breast cancer in BRCA1/2 mutation carriers." (PMID 33885953, 2021). "Of 828 patients with advanced malignancies including breast cancer undergoing testing with a 73 gene cfDNA assay, one or more pathogenic BRCA1/2 mutation was identified in 7.2% of patients, and both somatic and germline variants were detected." (PMID 33520111, 2021). "Breast cancer risk factors are related to the female’s age, parity, family history of breast cancer, especially first-degree relatives, radiation exposure, smoking, and the genetic factors of BRCA1 and BRCA 2 gene mutations." (PMID 34911515, 2021). "In summary, BRCA1 mutated breast cancers were characterized by reduced cyclin E1 T62 phosphorylation and elevated USP28 expression." (PMID 34465787, 2021). "Breast cancer (BC) risk for BRCA1 and BRCA2 mutation carriers varies by genetic and familial factors." (PMID 33597508, 2021). "As the first identified breast cancer associated gene, BRCA1 is closely associated with mammary gland development and tumorigenesis." (PMID 34815798, 2021). "The cumulative lifetime breast cancer risk was 59.1% (95% CI: 44.1–73.6%) for BRCA1 and 58.3% (95% CI: 43.2–73.0%) for BRCA2 carriers." (PMID 34063308, 2021). "Risk-reducing mastectomy (RRM) is often advocated for BRCA1/2 mutation carriers who face a heightened lifetime risk of breast cancer." (PMID 34070748, 2021). "BRCA2-associated breast cancers also tend to be poorly differentiated but are more often ER-positive than BRCA1 mutant counterparts." (PMID 34926274, 2021). "Women who carry a BRCA1 or BRCA2 pathogenic variant (PV) are at an increased risk of developing breast cancer." (PMID 34540661, 2021). "BRCA1/2 mutated genes, first identified in breast cancer, are independent risk factors in the initiation and progression of several human malignant tumors." (PMID 34497764, 2021). "A recent transcriptomic study reported similarity between germline and somatic mutations of BRCA1/2 genes in breast cancer in agreement with subtle differences in gene expression observed in this study." (PMID 33525353, 2021). "About 5-10% of all breast cancers can be attributed to hereditary genetic components and up to 25% of familial cases are due to mutations in BRCA1/2 genes." (PMID 34490083, 2021). "After analysis of inter- and intra-tumor heterogeneity of the BRCA1-deficient mammary tumors, we wanted to further explore how the mutant mammary cells transform into tumor cells." (PMID 34815798, 2021). "Accumulating evidence has shown that BRCA1 mutation is a crucial risk factor in multiple cancers, including breast cancer, skin cancer, ovarian cancer, and colorectal cancer." (PMID 34398824, 2021). "The cumulative risk estimates for developing breast cancer by age 80 are 70–90% for carriers of BRCA1 pathogenic variants and 60–70% for BRCA2 carriers." (PMID 34290354, 2021). "Of breast cancer cases, Breast Cancer Gene 1 (BRCA1) and Breast Cancer Gene 2 (BRCA2) mutations are the most commonly encountered CPGs." (PMID 34070674, 2021).
breast cancer (continued). "Poly(ADP-ribose) polymerase (PARP) inhibition in breast cancer mutant tumor cells induces synthetic lethality and has emerged as a promising anticancer therapy, especially in BRCA1/2 mutation carriers." (PMID 34253236, 2021). "While a meta-analysis of 18 studies suggested similar response rates for PARPi with germline and somatic BRCA1/2 mutations, less is known about the role of somatic mutations of BRCA1/2 in predicting response to PARPi in breast cancer." (PMID 34959671, 2021). "Any family history of breast cancer was associated with both P/LP BRCA1 variant (OR, 4.87; 95% CI, 2.82-8.42; P < .001) or a P/LP BRCA2 variant (OR, 3.07; 95% CI, 1.40-6.71; P = .005)." (PMID 33646313, 2021). "The important factors increase a man’s risk of breast cancer are: older age, BRCA2/BRCA1 mutations, increased estrogen levels, Klinefelter syndrome, family history of breast cancer, and radiation exposure." (PMID 34503097, 2021). "Pathogenic attenuations in either BRCA1 or BRCA2 account for 25–40% of familial breast cancers and up to 10% of all breast cancers." (PMID 35008774, 2021). "Approximately 75–80% of breast cancers that develop in women harboring deleterious BRCA1 mutations have a triple-negative phenotype and basal-like gene expression." (PMID 33753748, 2021). "ER- breast cancer more commonly involves mutation of DNA repair genes including BRCA1/2, PALB2 and members of the Fanconi Anemia pathway, which result in STING pathway activation." (PMID 34172750, 2021). "Inhibitors of PARP1 are already investigated due to their synthetic lethal effects with the combination of pre-existing BRCA1/2 (Breast Cancer gene 1/2) loss-of-function mutations." (PMID 33562002, 2021). "Several studies describe the role of physical activity and healthy diet in reducing breast cancer risk, also for subjects carrying BRCA1/2 mutations." (PMID 34552867, 2021). "Hereditary breast and ovarian cancer (HBOC) caused by germline BRCA1/2 gene pathogenic variant (gBRCAm) is predicted to be responsible for about 5% of all breast cancers and 15% of all ovarian cancers." (PMID 34071148, 2021). "TRIP13 overexpression correlates with BRCA1-deficiency in breast cancer cells and contributes to chemoresistance towards PARP inhibitors." (PMID 35198436, 2021). "UBE2W was abnormally expressed and significantly correlated with mismatch repair (MMR) gene mutation levels, DNA methyltransferase, and BRCA1/2 expression in breast cancer." (PMID 33931024, 2021). "In Świętokrzyskie Oncology Center in the south of Poland, 37% (7 out of 19) of germline pathogenic BRCA1/2 variants detected in breast cancer were reported in TNBC patients." (PMID 33918338, 2021). "PARP inhibitors (PARPi) including olaparib, niraparib, rucaparib, and talazoparib have been approved as monotherapy for patients with BRCA1/2-mutated ovarian cancers, breast cancer, pancreatic cancer, and prostate cancer." (PMID 33589588, 2021). "Gata3 deficient mammary tumors phenocopied Brca1 deficient tumors in the induction of EMT under the same genetic background." (PMID 34373738, 2021). "In total, eleven patients with detected BRCA1 variants had breast cancer, five patients had ovarian cancer, and two patients had breast and ovarian cancer." (PMID 34680878, 2021). "There is a difference in overall survival between breast cancer patients with BRCA1 and BRCA2 mutation." (PMID 33996049, 2021).